MIR103A1 (microRNA 103a-1)
Synonyms: hsa-mir-103-1; hsa-mir-103a-1; MIR103-1; MIRN103-1; mir-103a-1
Gene: MicroRNA gene on chromosome 5 (168,560,896 to 168,560,973, reverse strand). Ensembl gene ENSG00000199035.
Gene Ontology:
Biological process: miRNA-mediated post-transcriptional gene silencing
Cellular component: RISC complex
Homologues: Orthologues: chimpanzee ptr-mir-103-1 (100% identical), guinea pig MIR103A1 (100% identical), mouse Mir103-1 (100% identical), rat Mir103a1 (100% identical), pig ssc-mir-103-1 (99% identical), zebrafish dre-mir-107 (77% identical), zebrafish dre-mir-103 (76% identical), zebrafish mir107b (73% identical). Paralogues in human: MIR103A2 (81% identical), MIR107 (81% identical).